ISG15 (ISG15 ubiquitin like modifier)
Diseases named in the same sentence as ISG15 in open-access papers (continued):
Sharing a sentence is not in itself a finding about the gene and the disease.
infection (continued). "MVA-Δ3-ISG15AA infection in vitro and in vivo triggers an increase of Ifn-I transcription from 6 hours onwards, in correlation with an increase in Isg15 mRNA levels, and also an increase in soluble IFN-I." (PMID 37313341, 2023). "In this study, using a V5-specific antibody, we detected the presence of heterologous ISG15 both intracellularly and extracellularly after infection, with ISGylation mainly observed following infection with MVA-Δ3-ISG15GG virus." (PMID 37313341, 2023). "ISG15 is conjugated to de novo-synthesized proteins in a cotranslational manner, what facilitates ISGylation of viral proteins during infection." (PMID 37036376, 2023). "Overexpressing MIB2 significantly inhibited ISG15 protein levels, while knocking it boosted ISG15 protein expression during SCRV infection." (PMID 37652905, 2023). "qRT-PCR assay showed that eight antiviral-related mRNA including IRF3, IRF7, IKKβ, TBK1, IFIT1, IFI44, MX1 and ISG15 displayed significantly stronger and quicker response at early infection under 20 °C." (PMID 37627029, 2023). "Such antiviral activity is achieved through direct interaction of ISG15 with viral proteins or through the modulation of host proteins to limit the progression of the infection and to enhance immune responses." (PMID 37036376, 2023). "ELISA analysis showed that IFN-γ and ISG15 levels in cell culture supernatant decreased after H37Rv infection, while they significantly increased after LRRC25 silencing." (PMID 37894158, 2023). "As modulation of host genes by the Omicron subvariants infection in the lung periphery area, upregulation of Cxcl10, Isg15, and Mx-10 expression was observed in the BA.5-infected hamsters." (PMID 37488344, 2023). "When infection progressed, up-regulation of the following genes were detected exclusively in isg15 (FC of 0.93), rag1 (FC of 1.21), and perp (FC of 0.6), indicating a change of tendency and slight promotion of antiviral response." (PMID 37346045, 2023). "We observed that ASFV-Δ110-9L/505-7R infection increased HT-DNA-triggered transcription levels of Ifn-b, Isg56, Cxcl10, and Isg15 compared with ASFV-WT." (PMID 37162350, 2023). "A recent study pointed out that RNF213, an ISG15 interactor, can act as a sensor for ISGylated proteins to counteract infection." (PMID 36605987, 2022). "IFI44, ISG15, MX1, RSAD2, SAMD9 and TNFSF10 were chosen as they are infection-associated genes that show lower expression levels in Holstein infected cells compared to Sahiwal cells." (PMID 35061738, 2022). "ISG15 increases basal and infection-induced autophagy during Listeria monocytogenes infection by modifying mTOR, WIPI2, AMBRA1, and RAB7." (PMID 35159348, 2022). "An emerging theme from recent studies on ISG15 is its impact on innate immune responses to infection, both in its free and conjugated forms." (PMID 36416643, 2022). "The impact of ISG15 conjugation or binding to viral factors to inhibit infection has been extensively reviewed elsewhere, which points toward its antiviral nature." (PMID 36416643, 2022). "A supposed model is based on the localization of the ISG15 E3 ligase (HERC5) at the ribosome site where the proteins are co-translationally modified by ISG15 during infection, thus hampering with the function of newly translated viral proteins." (PMID 35562882, 2022). "The mRNA levels of IL-1β, IL-6 and TNF-α were significantly higher in the brains and lungs of ISG15-/- mice as compared with those of WT mice at different time points post infection." (PMID 36315588, 2022). "Knocking down ISG15 in human cells has also suggested an antiviral role of ISG15 during infection with numerous viruses, whereas other studies have suggested no role at all." (PMID 36146669, 2022). "We analyzed the secretion or expression of different immunomediators (cytokines CCL2, CXCL8, TNF-α, and interferon-stimulated gene ISG15) at different times following infection of PAMS." (PMID 35019713, 2022).
infection (continued). "A significant increase in N protein translational levels and virus titers at 48 h after PPRV infection in ISG15-silenced cells was observed compared with control and untreated cells at the same time postinfection." (PMID 36036587, 2022). "ISG15 expression and conjugation to targets is induced by a variety of processes, including infection, IFN‐α and ‐β signalling, ischemia, DNA damage, and aging." (PMID 35842904, 2022). "Using single-cell RNA sequencing of infected mouse caecum, we reveal that progression of infection results in cell damage and an expansion of enterocytes expressing of Isg15, potentially instigating the host immune response to the whipworm and tissue repair." (PMID 35365634, 2022). "The expressions of il10, nos2 and the ISGs isg15, and mx1 were only upregulated in tlr2−/− macrophages following infection, indicating that TLR4 controls the levels of these M(Kp) markers." (PMID 36337046, 2022). "The transcription levels of IFN-β and ISG15 were upregulated in a viral dose- and infection time-dependent manner." (PMID 36307867, 2022). "Several CC/CXC chemokines genes as well as antiviral genes, such as IRF7 and ISG15, were among the most upregulated genes throughout infection." (PMID 35812400, 2022). "Work on bone‐marrow derived macrophages from ISG15–/– mice showed that ROS levels were actually lower in cells from KO mice during infection with vaccinia virus." (PMID 35842904, 2022). "Infection of myeloid cells with recombinant MHV harboring the nsp14-Y414A mutation (rMHVnsp14-Y414A) resulted in upregulated expression of IFN-I and ISG15 mainly via MDA5 signaling and in reduced viral replication compared to that of wild-type rMHV." (PMID 35073761, 2022). "In PRV-infected PK15 cells, the greater levels of free ISG15 and ISG15 conjugates were observed at 24 hours post-infection (hpi), even at relatively low MOIs (0.5, 1 and 5)." (PMID 36315588, 2022). "Knocking down ISG15 in human cells has also suggested an antiviral role for ISG15 during infection with numerous viruses, while other studies have suggested no role at all." (PMID 36315588, 2022). "We thus carried out qRT-PCR to screen for the expression of RLRs (RIG-I and MDA5) as well as IFN-β and ISG15 in SC at 6 h and 24 h post infection." (PMID 36611893, 2022). "A549 cells were treated with ESCRT siRNA and transfected with either GFP as a control or ISG15 construct before LGTV infection." (PMID 34851141, 2022). "This review describes recent findings on the role of ISG15 in antiviral responses in human infection models, with a particular emphasis on autophagy, inflammatory responses and cellular metabolism combined with viral strategies of counteracting them." (PMID 36416643, 2022). "Here, the authors show how larvae create tunnels inside the gut lining and reveal the early host response to infection via Isg15 in mice and murine caecaloids." (PMID 35365634, 2022). "Upon infection with R. equi, cGAS KO macrophages had reduced levels of Ifnb, Isg15 and Ifit1 transcripts, and a significant but less dramatic reduction in Tnfa." (PMID 34473814, 2021). "IE1 is one of the first proteins expressed by HCMV following infection, thus by targeting ISG15 by a virion-associated protein as well as IE1, HCMV ensures a rapid counterattack to host-mediated ISG15 upregulation as an antiviral measure." (PMID 34440891, 2021). "For example, IRF7 overexpression inhibited SGIV replication, and ISG15 was able to decrease RGNNV infection in grouper cells." (PMID 33767703, 2021). "Transcriptome analysis of the nasal turbinates and lungs indicated that female ferrets had significant increases in interferon response genes (OASL, MX1, ISG15, etc.)on day 2 post infection which was delayed in aged males." (PMID 33469587, 2021). "Nevertheless, ISG15’s antimicrobial activity is still considered as its foremost function which prompted additional proteomics studies in the context of infection." (PMID 34447387, 2021).
infection (continued). "Results from an experimental mouse model showed that several ISGs, among which is ISG15, were upregulated following infection of the brain by CHIKV." (PMID 33799906, 2021). "During ISAv infection, the innate immune response included increased expression of Mx and ISG15 via an IFN-independent mechanism." (PMID 35046944, 2021). "Since individual foals varied in their response to infection and having shown that pre- and post-challenge cytokine levels were similar in uninfected foals, we next focused on infected foals and compared baseline ISG15 levels with post-infection levels." (PMID 34473814, 2021). "Then, knockdown or overexpression NARL also can significantly inhibit or promote the expression levels of TNF-α, MX1, and ISG15 upon SCRV infection." (PMID 33581111, 2021). "At day 3 post infection there was an increase in Ifnα2, Isg15, and Stat1 gene expression detected in young adult lung in response to either H1N1 or H3N2." (PMID 34829979, 2021). "ISG15 mRNA levels have also been identified as a potentially valuable biomarker in the context of active human TB, as ISG15 can promote early MTB replication although it plays protective roles during the later stages of infection." (PMID 34490145, 2021). "ISG15 expression was also decreased in IL16-expressing cells after PR8 infection, suggesting that IL16 overexpression represses type I IFN-β and ISG expression." (PMID 34630361, 2021). "The A549 cells lacking the XRN1 protein showed increased IFN-β, IFIT1, IFIT3, and ISG15 expression compared with the A549 control cells at 4 to 8 h after WSN infection." (PMID 34311580, 2021). "Infection with either HO or KY alone had similar inhibitory effects on most ISGs (ISG15, GBP4, HERC5, RSAD2, DDX58, and IFIT3), although a slightly greater inhibitory effect of HO was observed on IFI27 and MX1." (PMID 33898551, 2021). "Genes encoding interferons (Ifnb, Ifnl2 and Ifnl3), chemokines (Ccl7, Ccl5, and Cxcl10), and ISGs (Ifit1, Ifit2, Ifit3b, Oas3, Ifi44, Rsad2, and Isg15, among others) were prominently represented among those induced by infection in Ifnar1-/- mice." (PMID 34591933, 2021). "They demonstrated that both free and binding ISG15 expression is upregulated after pathogen infection, and both forms of ISG15 exhibit antiviral activity." (PMID 34901029, 2021). "Transcripts of Ifnb (B) or ISGs (Cxcl10, Isg20, Ccl5, Isg15) (C) were determined at 6 hr after infection." (PMID 32886065, 2020). "Transcripts of Ifnb (A) or ISGs (Cxcl10, Isg20, Ccl5, Isg15) (B) were determined 6 hr after infection." (PMID 32886065, 2020). "Our newly developed cell lines and infection model will pave the way for further studies investigating the regulatory mechanisms of ISG15 during the antiviral response." (PMID 32423918, 2020). "ISG15 expression of PAMs infected with CSFV (MOI = 1) was analyzed at the indicated times post-infection." (PMID 32093773, 2020). "To understand the antiviral response in the CHME3 human microglial cell line, we next investigated the expression levels of antiviral genes MDA5, RIG-I, MX1, IRF7, IFNβ, and ISG15 following infection with PRVABC59 ZIKV." (PMID 32373079, 2020). "In the total RNA fraction, ISG15 was upregulated at 12 h of infection and onwards while viperin expression was upregulated at 6 h of SAV-2 infection and onwards." (PMID 32922394, 2020). "PRRSV-N protein levels decreased as the dose of recombinant sISG15 increased, suggesting that the ISG15 treatment of PAMs conferred resistance to infection or inhibition of PRRSV replication." (PMID 32927637, 2020). "RT-qPCR analysis revealed that the IFN-β gene, RIG-I, and ISG15 were all induced by infection with both NoV and NoVΔB2 in C57BL/6 and Rag1−/− mice compared to that with the infection of Stat1/2−/− mice." (PMID 32753500, 2020). "Isg15 mRNA was higher in brains of WT- and Y114A-infected mice than G32S-infected mice throughout the infection and in the spinal cord at 4 days (P < 0.0001)." (PMID 32047134, 2020).
infection (continued). "In summary, a sandwich ELISA incorporating homemade anti-ISG15 Mab detected ISG15 secretion induced by PAMs infection with a PRRSV vaccine strain." (PMID 32927637, 2020). "(A) RT-qPCR of Isg15 expression after 4 and 8 hr of infection with M. leprae (MOI = 50) in Lrrk2 KO BMDMs and HET controls." (PMID 32057291, 2020). "To confirm these results using the FMDV host-specific ISGylation machinery during infection, we cloned the porcine ISG15 in a replication-defective human adenovirus type 5 (Ad5) vector and examined its antiviral activity in swine cells." (PMID 32295921, 2020). "Innate antiviral defense genes, namely ISGs (e.g., MX1, OAS1, STAT1, STAT2, ISG15), are upregulated early in fatal infection and their expression increases dramatically throughout infection indicative of dysregulated innate immune response." (PMID 32992829, 2020). "Whereas ISG15 sites induced following infection with Listeria in wild-type mice (cluster 2) have a 31% overlap with acetylation." (PMID 31772204, 2019). "Comparison with ubiquitinated proteins suggested a lower percentage of modification of infection-induced ISG15 targets than that of infection-induced ubiquitin targets." (PMID 31772204, 2019). "Our strategy reveals 930 endogenous sites on 434 ISG15 substrates in the liver in the context of a clinically relevant infection." (PMID 31772204, 2019). "Conversely, HCMV IE1 and UL26 suppress the infection-induced ISGylation, to counteract the ISG15-mediated immune defense." (PMID 31798565, 2019). "These patterns of enrichment suggest that certain ubiquitin modifications are replaced with ISG15 modifications following infection." (PMID 31772204, 2019). "Here, we contribute a large-scale map of endogenous ISG15 sites in a relevant infection setting in vivo." (PMID 31772204, 2019). "The classical ISGs were strongly induced by CDV-infection with particularly high levels for Isg15, Ifi44l, Isg56, Oas2 and Mx2 (fold change up to 928.35, 419.93, 179.05, 173.57 and 147.59)." (PMID 30939763, 2019). "Levels of TNF-α and CCL2 were significantly elevated from pre-clinical to early-stage infection, and IL-6, IL-12b, CCL3, CCL12, and ISG15 levels were significantly elevated from pre-clinical to late-stage infection." (PMID 31790513, 2019). "Post-translational modification of host and viral proteins by ubiquitin (Ub) and Ub-like proteins, such as interferon stimulated gene product 15 (ISG15), plays a key role in response to infection." (PMID 30629698, 2019). "We found that the mRNA expression levels of ZAP, MX2, MX1, PKR, OASL, and ISG15 were significantly higher in the Lp-1s treated group than in the TGEV infected group at various points after infection." (PMID 31781061, 2019). "In fact, ISG15−/− fibroblasts isolated from such patients and primed with type I IFN were less susceptible to infection with HCMV than controls." (PMID 31921100, 2019). "In contrast to VA1-infected C68 HIE, Sindbis virus infection and poly I:C treatment strongly upregulated ISG15 gene expression in C68 HIE at day 1 post infection/treatment." (PMID 31671153, 2019). "The elevation of the ISG15 pathway in this specific tissue is ideally placed to prevent challenge by the most likely natural route of infection." (PMID 31396205, 2019). "In order to better understand the consequences of ISG15 modification on protein fate, we systematically identified endogenous ISG15 substrates following infection in vivo with the bacterial pathogen, Listeria monocytogenes." (PMID 31772204, 2019). "On the other hand, C68 and I124 HIE responded with increases in transcript levels of IFN-β, IFN-λ, and ISG15 to VA1 infection over the 3 day timecourse." (PMID 31671153, 2019). "The authors noted that 1α,25(OH)2D treatment prior to or post-infection downregulated IL-6 and IL-8 RNA levels and decreased the levels of infection-induced TNFα, IFNβ, and ISG15." (PMID 30115864, 2018).
infection (continued). "Two cysteine residues in the hinge domain are necessary determinants for ISG15 to induce increased cytokine levels during infection." (PMID 29891555, 2018). "To study the effect of MTX treatment on the antiviral innate immune responses of HSF exposed to CHIKV, we evaluated by qRT-PCR the expression of IFN β and ISG15 antiviral genes at 24H post-infection." (PMID 30074983, 2018). "We therefore analyzed the DC compartment of the peritoneal exudate of Toxoplasma-infected ISG15−/− and C57BL/6 mice upon infection, the latter left untreated or treated with recombinant ISG15 or with ISG15-C76S/C144S." (PMID 29891555, 2018). "Increased ISG15 is concurrent with an influx of IL-1β–producing CD8α+ dendritic cells to the site of infection." (PMID 29891555, 2018). "We can conclude extracellular ISG15 is produced as a consequence of an active infection to work as a cytokine-like molecule." (PMID 29891555, 2018). "This demonstrates that ISG15-dependent modulation of cytokine levels during the early phase of infection is dependent on active invasion and replication of the parasite and can be enhanced by administration of additional recombinant ISG15 into the serum." (PMID 29891555, 2018). "Mice treated with ISG15-C76S/C144S resembled untreated wild-type mice, confirming that cysteine residues of ISG15 are critical to facilitate CD8α+ DC recruitment to the site of infection." (PMID 29891555, 2018). "This suggests that enhanced ISG15 release during the early phase of infection is dependent on active invasion and replication of the parasite." (PMID 29891555, 2018). "In parallel PI3Kγ KO cells were infected and harvested 8 h after infection to evaluate the downstream antiviral molecule ISG15." (PMID 29867955, 2018). "We also analyzed the serum of Toxoplasma-infected mice by SDS-PAGE and immunoblotting and confirmed the release of ISG15 early upon infection." (PMID 29891555, 2018). "MTX 1μM did not affect significantly the relative expression of IFN β and ISG15 in mock-infected control cells as well as after CHIKV MOI1 infection." (PMID 30074983, 2018). "When infection occurs with a live, active replicating parasite, we observed an increase in ISG15 levels as compared with gamma-irradiated or heat-killed parasites in the serum at day 4 p.i.." (PMID 29891555, 2018). "The presence of free ISG15 enhances the production of IL-1β by CD8α+ DCs present at the site of infection." (PMID 29891555, 2018). "We found that ISG15 levels correlate with an increase of IL-1β levels in the serum and with increased number and frequency of CD8α+ conventional DCs at the site of infection." (PMID 29891555, 2018). "Early studies using ISG15-/- mice demonstrated that ISG15 has a protective effect against lethal infection by Influenza virus, Herpes Simplex virus (HSV-1) and Sindbis virus (SINV)." (PMID 30428561, 2018). "We noticed that Toxoplasma-infected ISG15−/− mice presented with DC levels comparable to or lower than naive mice at the site of infection." (PMID 29891555, 2018). "The cysteine residues of free ISG15 are required to trigger an increase in CD8α+ DCs producing IL-1β at the site of the infection." (PMID 29891555, 2018). "The levels of representative ISG mRNAs, STAT1, ISG15, and viperin, peaked at around 9 h post infection and with the exception of STAT1 remained at high levels in infected cells." (PMID 28087593, 2017). "The Mx1 expression reached its peak at 24 h post-infection, whereas Isg15 expression declined from the peak at 6 h." (PMID 27826541, 2016). "It revealed that both mouse and human responses along PC1 (the infection response) are largely driven by interferon-response genes (e.g. ISG15, IFIT1)." (PMID 27193691, 2016). "To explore the consequences of expressing ISG15 in a setting detached from infection, we performed mass spectrometry on ISG15 immunoprecipates prepared from IFN-α treated plasmablasts." (PMID 27357150, 2016).